PGR (progesterone receptor)
Diseases named in the same sentence as PGR in open-access papers (continued):
Sharing a sentence is not in itself a finding about the gene and the disease.
tumor (continued). "Multivariate analysis demonstrated that, in addition to the common risk factors such as larger tumor size, lymph node involvement, estrogen receptor/progesterone receptor-negative tumors, and HER2/neu-positive tumors, overexpression of pAkt significantly was associated with a decrease in 5-year DFS." (PMID 18184439, 2008). "Furthermore, the ratio of the 50 kDa fragment to the mature fibulin-1 polypeptide correlated with the level of oestrogen receptor α (Spearman correlation coefficient, rs=0.49, P<0.003, n=36) and progesterone receptor (rs=0.43, P=0.008, n=36) expression in the tumour specimens." (PMID 12644824, 2003). "As in case of Akt-1, we could not find any significant association of pAkt with nodal status, tumour size, ER, PgR or Bcl-2 but we did find a strong negative association with SPF." (PMID 11870534, 2002). "Indeed, activation of both the progesterone receptor (PR) and the androgen receptor (AR) have been shown to reprogram the ER cistrome: reinstalling a gene-expression program of favorable outcome and repressing ER-regulated cell cycle genes, whilst upregulating known tumor suppressors." (PMID 41261233, 2026). "We calculated the conversion rate and the status of ER, PgR and HER2 frequently changed between primary tumor and liver metastasis." (PMID 41511682, 2026). "Immunohistochemical staining demonstrated that the tumor cells were positive for CD34, desmin, androgen receptor, and progesterone receptor." (PMID 41529035, 2026). "For example, the PGR and GATA3 genes concordantly showed a higher methylation pattern, resulting in a lower RNA expression in the tumor regions." (PMID 41187747, 2025). "Hormone receptor statuses—estrogen receptor (ER), progesterone receptor (PR), and HER-2/neu—provided insight into tumor subtypes and their potential influence on treatment response." (PMID 40427125, 2025). "In both groups, women who received anthracyclines were younger and of higher socio-economic status, had more advanced stage at diagnosis, higher grade tumours, and more often HER2, oestrogen, or progesterone receptor-positive tumours." (PMID 40542432, 2025). "Additional immunohistochemical examination demonstrated that the tumor cells were positive for CD10, vimentin, progesterone receptor (PR), and neuron-specific enolase (NSE), and the low Ki-67 index indicated minimal proliferative activity." (PMID 41426933, 2025). "Prognostic staging includes anatomical TNM staging, tumor grading, and tumor receptor status: HER-2, estrogen receptor, and progesterone receptor." (PMID 39860032, 2025). "This downregulation correlates with key clinicopathologic markers, including estrogen receptor (ER), progesterone receptor (PR), and HER2 status, suggesting that PIEZO2 expression is closely aligned with tumor hormonal signaling profiles." (PMID 41327436, 2025). "Based on tumor microenvironment composition, we defined two AGCT subtypes: AGCT-1 and AGCT-2 with distinct FOXL2+ cell distributions, differences in progesterone receptor expression, and unique transcriptomic profiles." (PMID 41042551, 2025). "Specimens were classified based on age, tumor size, tumor, node, metastasis (TNM) stage, progesterone receptor expression, and ER expression." (PMID 40181838, 2025).
tumor (continued). "Immunohistochemical staining demonstrated that the tumor cells were positive for epithelial membrane antigen (EMA), somatostatin type 2 receptor, progesterone receptor (PgR), and Vimentin." (PMID 40663004, 2025). "Elevated HOTAIR levels can inhibit the activity of tumor suppressors such as protocadherin 10 (PCDH10), progesterone receptor (PGR), protocadherin β5 (PCDHB5), and junctional adhesion molecule 2 (JAM2), leading to tumorigenesis." (PMID 40129920, 2025). "Immunohistological examination showed that the tumor cells were positive for epithelial membrane antigen (EMA), estrogen receptor (ER), and progesterone receptor (PgR)." (PMID 40766037, 2025). "Tumor cells were strongly positive for CD10, estrogen receptor, and progesterone receptor, whereas, a few tumor cells in an area of epithelial-like configuration were positive for Desmin." (PMID 39121276, 2024). "Compared with core needle biopsy, changes of estrogen receptor (ER), progesterone receptor (PR), HER2, and Ki-67 expressions in residual tumor after neoadjuvant HER2-targeted treatment were reported." (PMID 38582875, 2024). "Despite these advances, most doctors still rely on established clinicopathologic features and widely available tumor markers like estrogen receptor (ER), HER2 and progesterone receptor (PR)." (PMID 37962462, 2024). "Thus, luminal HER2 (ER+ and PgR+) tumors had the highest frequency (28%) of being HH tumors in our study, and these observations were essentially consistent with the concept of tumor heterogeneity, where a biological diversity of cancer cells is found within a tumor." (PMID 38473420, 2024). "Genetic and pharmacological PGR inhibition resulted in a marked attenuation of macropinocytosis in PDAC cells and subcutaneous tumor models, indicating the involvement of this receptor in macropinocytosis regulation." (PMID 38424455, 2024). "The spatial transcriptome data identified differential expression of DDX3Y, PGR and NKX2‐2 between tumour samples and normal samples." (PMID 39548559, 2024). "Nonetheless, this study only showed the relation between PGR expression and the overall survival in PDAC patients through univariate survival analysis, ignoring the influence of multiple factors, such as tumor stage and differentiation degree." (PMID 38424455, 2024). "IHC analysis revealed triple expression of hormonal receptors (estrogen receptor, progesterone receptor, and HER2), supporting the mammary gland origin of the tumor." (PMID 38572338, 2024). "The OR for ER and PgR (neg vs. pos) was 0.41 and 0.57, respectively, while the OR for HER2 (pos vs. neg) was 0.62 and for Ki-67 (high vs. low) tumour it was 0.49." (PMID 38454634, 2024). "Specific miRNAs have been identified that modulate the expression of critical receptors such as estrogen receptor (ER), progesterone receptor (PR), and HER2, directly influencing tumor progression and treatment response." (PMID 39850811, 2024). "Currently, this neoplasia is classified into distinct subtypes based on tumor staging/grading and the expression of the estrogen receptor (ESR1), progesterone receptor (PgR), human epidermal growth factor receptor 2 (HER2), and the proliferation marker Ki-67." (PMID 37958677, 2023). "She underwent neoadjuvant systemic therapy (Letrozole → Taxol + Herceptin) depending on the histology of the biopsy specimen (hormonal therapy and ER-positive, PgR positive, HER2 positive, nuclear grade 3) and achieved a good tumor response." (PMID 38054154, 2023).
tumor (continued). "Many of these tumours display high expression of proliferation and DDR pathway modules compared with cluster 1 and low expression of ESR1/PGR." (PMID 37574209, 2023). "Significantly less suppression occurred in PgR- vs PgR + and HER2 + vs HER2- tumours which remained apparent after adjustment for 2-week sample type." (PMID 37046348, 2023). "Biological markers, such as histological grade, estrogen-receptor (ER), progesterone-receptor (PR), human epidermal growth factor receptor 2 (HER2), and nuclear protein Ki-67 status, have been used for tumor staging." (PMID 37590284, 2023). "There are different subtypes of BC based on the expression of hormone receptors (HR), including estrogen receptor (ER) and progesterone receptor (PR), and human epidermal growth factor receptor 2 (HER2) in the tumor cells." (PMID 36602530, 2023). "Repeated biopsy of the liver metastasis revealed an ER‐positive, PgR‐positive, and HER2‐negative tumor." (PMID 37361653, 2023). "Most prognostic factors, such as tumour size, histological grade, TNM stage, progesterone receptor and HER2 expression, showed insignificant differences in mast cell density." (PMID 37928785, 2023). "17β-estradiol and progesterone monotherapies have the same anticancer effects and enhance the tumor-killing effects of CRC in men through the promotion of androgen deprivation mediated by ERβ and PGR, while also blocking oncogenic pathways regulated by ERα." (PMID 38115900, 2023). "ITPR1 was negatively correlated with tumor size, tumor lymph node metastasis (TNM) staging, lymph node metastasis (LNM), estrogen receptor (ER), progesterone receptor (PR) and HER2 status (P < 0.05)." (PMID 35313846, 2022). "This disease is separated into distinct subtypes defined by the expression of estrogen receptor (ER), progesterone receptor (PR), and/or human epidermal growth factor receptor 2 (HER2) within the tumor." (PMID 35406623, 2022). "The tumor cells were diffusely positive for epithelial membrane antigen (EMA), and many cells were stained with progesterone receptor (PR)." (PMID 36654535, 2022). "Lower TRIM4 and higher SET expression levels, respectively, were related to larger tumor size and lymph node metastasis, whereas they were unrelated to age, histological grade, HER‐2, PGR, or Ki‐67 expression." (PMID 35843886, 2022). "Intrinsic tumor subtypes were determined using both PAM50- and IHC-based detection of estrogen receptor, progesterone receptor, Ki-67, epidermal growth factor receptor, and cytokeratins 14 and 5/6." (PMID 35568835, 2022). "Because the tumor subtypes were decided based on a combination of estrogen receptor (ER), progesterone receptor (PR), and HER2 status, only tumor subtype was included in the multivariable model to avoid collinearity of variables." (PMID 34103577, 2021). "Triple-negative disease (ER-, progesterone receptor-, and HER2-negative) is typically of higher grade and more aggressive than tumours with other receptor profiles." (PMID 33715004, 2021). "Chi-square test and Fisher’s exact test showed SKA3 expression was related to age, tumor (T) classification, node (N) classification, tumor-node-metastasis (TNM) stage, estrogen receptor (ER), progesterone receptor (PR), molecular subtype, and race." (PMID 34993016, 2021). "Growing lesions gradually increase their tumor cell density and overexpress HER2, which up-regulates the expression of miR-9-5p and miR-30a-5p, leading to the down-regulation of PGR in the mouse BC model." (PMID 34638241, 2021).
tumor (continued). "These include the human epidermal growth factor receptor-2 (HER-2), estrogen receptor (ER), progesterone receptor (PR) markers, and the triple-negative breast cancer (TNBC) markers, which further influence the tumor characteristics and prognosis." (PMID 34638847, 2021). "A recent study in PgR-low/null tumors defined phospho-PgR target gene sets (ERBB2, PAX2, AHR, AR, and RUNX2) which regulate cancer stem cell biology and increase tumor heterogeneity." (PMID 34638241, 2021). "It is a highly heterogeneous disease that is usually characterized by estrogen receptor (ER), progesterone receptor (PR), and epidermal growth factor receptor 2 (HER2) status of the primary tumor." (PMID 33547275, 2021). "Immunohistostaining studies revealed that the tumor cells were positive for vimentin, synaptophysin, cluster of differentiation (CD) 56, β-catenin, CD10, and progesterone receptor." (PMID 33650037, 2021). "Immunohistochemical studies revealed that the tumor cells were positive for vimentin, synaptophysin, CD56, β-catenin, CD10, and progesterone receptor." (PMID 33650037, 2021). "Tissue-based biomarkers, including the expression of estrogen receptor (ER), progesterone receptor (PR), and human epidermal growth factor receptor 2 (HER2), have been integral in subtyping of tumours, prognostication, and choice of systemic therapies." (PMID 33671468, 2021). "Although some studies have reported age, site, ER positivity, PgR positivity, HER2 positivity as predictors of SLNM, the most commonly reported predictors are tumor size, lymphatic invasion, and pathological nuclear grade." (PMID 32590956, 2020). "The protein expressions of ER, PgR and HER2/neu of the tumor tissues were evaluated by using immunohistochemistry analysis." (PMID 33112549, 2020). "By contrast, we found that MET modified the nuclear levels of immunoreactive ERα, PGR, and KLF9 proteins in tumor tissues and preferentially affected GE relative to ST." (PMID 32046384, 2020). "TNBC tumors lack estrogen receptor (ERα), progesterone receptor (PR), and HER2 (ErbB2) and exhibit increased glutamine metabolism, a requirement for tumor growth." (PMID 32034133, 2020). "Known major prognostic factors found so far include TNM stage, estrogen receptor (ER), progesterone receptor (PR), and human epidermal growth factor receptor 2 (HER2), however, most of these prognostic factors were for the character of the tumor itself." (PMID 32887448, 2020). "ER-, PgR- and HER2-positivity, the tumor size of pT2, and the nodal status of pN1 were significantly associated with the downstaging, while histological grade 3 and TN subtype were associated with the upstaging." (PMID 32472474, 2020). "The primary tumor type was HRBC in 76.0% of cases, and the frequencies of change in the ER, PgR, and HER2 statuses between the surgical and recurrent specimens were similar to those in previous reports." (PMID 32248830, 2020). "BCS, breast-conservation surgery; ER, estrogen receptor; HER2, human epidermal growth factor receptor 2; PR, progesterone receptor; MAST, mastectomy; N, nodal; RT, radiotherapy; T, tumor." (PMID 32320950, 2020). "In this new staging system, the ER, PgR, HER2, and tumor grade were incorporated into the prognostic stage definition." (PMID 32472474, 2020). "The tumor location, WHO grade, Ki67-labeling index (LI), progesterone receptor (PR) expression, and histological types were studied in premenopausal women with and without hormone-related conditions were compared." (PMID 33363003, 2020).
tumor (continued). "For instance, the methylation of progesterone receptor (PGR), hydroxysteroid 17-beta dehydrogenase 4 (HSD17B4), and cadherin 13 (CDH13) genes in both HER2 positive BCAFs and tumour cells was found to enhanced BC progression and invasion." (PMID 33066013, 2020). "We also analyzed the associations of CCDC170, IRE1 and XBP1 mRNA levels with clinicopathologic characteristics such as ERα, progesterone receptor (PR), Her2 and Ki67 levels, the PAM50 subtype, tumor size, lymph node status and TNM stage in TCGA and GEO." (PMID 33291081, 2020). "In the low-level tumor samples, the middle- to high-level FGF2 was related to cancer with a low progesterone receptor A isoform than B isoform ratio." (PMID 32775417, 2020). "Key eligibility criteria were: basal-like BC (estrogen and progesterone receptor < 1%, HER2-negative, cytokeratin 5/6 or epidermal growth factor receptor positive by immunohistochemistry), tumor size > 2 cm or <2 cm with nodal involvement." (PMID 31398896, 2019). "Treatment beyond surgery, chemotherapy, and radiotherapy is directed according to ER, PgR, and HER2 status, with endocrine therapy or trastuzumab available for patients with hormone receptor positive and HER2 positive tumours, respectively." (PMID 31769425, 2019). "Kaplan-Meier analysis indicated that patients presenting with reduced ITM2A expression exhibited poor overall survival, and expression significantly correlated with age, progesterone receptor status, TNM classification and tumor stage." (PMID 31438969, 2019). "These include histological type, histological grade, lymphovascular invasion, lymph node metastases, and the status of hormonal receptors—estrogen receptor (ER), progesterone receptor (PR), and human epidermal growth factor (HER2) status of the tumor." (PMID 30131927, 2018). "However, it is unclear whether obesity impacts the tumorigenesis of all breast cancers or only certain breast cancer subtypes as defined by the tumor protein expression status of the estrogen receptor (ER), progesterone receptor (PR), and human epidermal growth factor receptor 2 (HER2)." (PMID 29357906, 2018). "Several factors influence poor prognosis in the young subgroup, such as higher tumour grade at diagnosis, high tumour proliferation, increased expression of HER-2 (ERB-B2) and reduced expression of both estrogen (ER) and progesterone receptor (PR)." (PMID 29545918, 2018). "ADORA2B-expression was significantly correlated with ER (P < 0.01), PgR (P = 0.027), EGFR (P < 0.01), and tumor size (P = 0.037), and was an independent prognostic factor for outcome (P = 0.036)." (PMID 30349649, 2018). "Immunohistochemically, the tumor cells stained positively for CD34, estrogen receptor (ER), and progesterone receptor (PgR) and negatively for S-100, EMA, CK19, CD99, HMB45, and α-smooth muscle actin." (PMID 28831707, 2017). "With regard to the surgical factors, the surgery type, tumor-node-metastasis (TNM) stage, estrogen and progesterone receptor (ER and PR) status, histological type, and chemotherapy use showed significant differences between groups." (PMID 29163846, 2017). "Immunohistochemistry (IHC) study was performed on type I EC tumor samples using five adipokines (SPARC, RBP4 (Retinol Binding Protein 4), adiponectin, TNF α, IL-6) and hormonal receptors (estrogen receptor and progesterone receptor)." (PMID 28505082, 2017). "Immunohistochemically, tumour cells showed positive immunostaining with CD56, vimentin, NSE, β-catenin, progesterone receptor." (PMID 29187952, 2017). "Immunohistochemically, the tumor cells showed cytoplasmic staining for smooth muscle actin (SMA) and desmin, and nuclear staining for estrogen receptor (ER) and progesterone receptor (PR)." (PMID 28533481, 2017). "Tumors were classified according to the primary tumor TNM stage, histological type, grade, and presence of estrogen receptor (ER), progesterone receptor (PR), and ERBB2 (HER2) amplification." (PMID 28810143, 2017).